BRCA1 (BRCA1 DNA repair associated)
Diseases named in the same sentence as BRCA1 in open-access papers (continued):
Sharing a sentence is not in itself a finding about the gene and the disease.
ovarian carcinoma (continued). "Numerous studies have shown that targeting PARP 1 with specific inhibitors may improve prognosis for breast or ovarian cancer patients with mutated BRCA1/2 genes, which are involved in homologous recombination repair." (PMID 39866010, 2025). "It is currently mainly used to treat breast and ovarian cancers related to BRCA1/2 mutations." (PMID 40299423, 2025). "Furthermore, prior studies investigating PARP inhibitors in women with relapsed platinum-resistant ovarian cancer have shown that treatment response is largely influenced by BRCA1/2 mutation status." (PMID 40427127, 2025). "In cases such as breast and ovarian cancer, the detection of BRCA1 and BRCA2 mutations facilitates targeted interventions, including chemoprevention and risk-reducing surgeries, which have proven efficacy in lowering the incidence of cancer in high-risk populations." (PMID 41541272, 2025). "In BRCA1-deficient ovarian cancers, STING has a dual role in modulating the immune environment." (PMID 39949780, 2025). "One patient with LMD from ovarian cancer showed a BRCA1 mutation." (PMID 40264106, 2025). "Multiple guidelines indicate that high-risk individuals and families benefit from precise risk stratification, including BRCA1/2 carriers initiating breast MRI screening at age 25, and prophylactic salpingo-oophorectomy reduces ovarian cancer mortality in BRCA+ individuals." (PMID 41301752, 2025). "Notably, germline BRCA1/2-mutated ovarian cancers or those with high HRD status exhibit longer progression-free survival with PARPi therapy." (PMID 40948682, 2025). "Germline mutations in BRCA1/2 are responsible for 10–15% of ovarian cancer cases." (PMID 40427158, 2025). "Finally, we show that chemical inhibition of SPT1 increases the efficacy of Olaparib in BRCA1-deficient breast and ovarian cancer cells." (PMID 40527886, 2025). "Similarly, increased levels of KSRP expression in BRCA1-mutated breast and ovarian cancers were observed through the interaction between KSRP and lncRNA LINC01305." (PMID 40699755, 2025). "Indeed, it is well known that ovarian cancers with germline or somatic BRCA1/2 mutations and GIS can undergo reversion mutations to restore BRCA1/2 expression and restore HR proficiency without altering the high GIS." (PMID 40390012, 2025). "In conclusion, retrospective cohort studies suggest that BRCA1/2-mutated ovarian cancers often present with a substantial disease burden at diagnosis; however, peritoneal lesions tend to exhibit less infiltrative architecture, potentially facilitating easier surgical excision." (PMID 40868967, 2025). "Therefore, we characterised the ID8 model of ovarian cancer, with matched cell lines with specific mutations in Brca1 and Brca2." (PMID 40977519, 2025). "Approximately 14% of ovarian cancer cases are a result of mutations in BRCA1 or BRCA2 genes." (PMID 40894326, 2025). "Therefore, we propose SOX5 as a promising therapeutic target for overcoming PARP inhibitor resistance in BRCA1/2-mutated breast and ovarian cancer." (PMID 40274769, 2025). "Currently approved PARP inhibitors for ovarian cancer, such as olaparib, niraparib, and rucaparib, have demonstrated significant clinical efficacy, particularly in patients with BRCA1/2 mutations, where they effectively induce tumor cell death through the synthetic lethality mechanism." (PMID 40395324, 2025). "However, none of the existing screening programs have incorporated genetic testing for hereditary mutations, particularly pathogenic variants in the BRCA1/2 genes, despite their well-established role as major risk factors for breast and ovarian cancer." (PMID 40567951, 2025). "Therefore, the present study aimed to address this gap by conducting a systematic review and meta-analysis to examine the prognostic implications of BRCA1/2 mutation locations in epithelial ovarian cancer." (PMID 40427158, 2025).
ovarian carcinoma (continued). "The SOLO‐1 trial showed that first‐line maintenance therapy with Olaparib, an oral poly‐adenosine diphosphate‐ribose polymerase inhibitor (PARPi), significantly improved survival in patients with newly diagnosed advanced ovarian carcinoma that had germline or somatic BRCA1/2 gene mutations." (PMID 40891252, 2025). "Likewise, BRCA1 methylation in ovarian cancer (~16%) mirrors BRCA1 genetic loss and correlates (in certain assay types) with treatment response, supporting methylation as both a functional alteration and a biomarker across cancers." (PMID 41150792, 2025). "Similarly, secondary mutations reinstating BRCA1/2 function have been identified in 46% of platinum-resistant or recurrent ovarian cancer with BRCA mutations." (PMID 40460005, 2025). "Moreover, the types of BRCA1/2 mutations also differ substantially from foreign data, likely contributing to discrepancies in breast and ovarian cancer risk for BRCA1/2 carriers in China." (PMID 40567951, 2025). "Consequently, miR-622-mediated HR restoration reduces sensitivity to PARP1 inhibitors in BRCA1-mutated ovarian cancer (OvCa) cells." (PMID 41008855, 2025). "Furthermore, PARPis, which target the DNA repair mechanisms in ovarian cancer cells, represent a recent breakthrough, particularly for patients with BRCA1/2 mutations." (PMID 40395324, 2025). "CD6, CXCL9, and CXCL13 were associated with favorable outcomes in BRCA1-mutant ovarian cancers." (PMID 40647506, 2025). "A cis-acting germline alteration located in the 5’ UTR of BRCA1 gene (c.-107A > T, rs2154580237), has been previously identified in 2018 in two British families and was found to segregate with BRCA1 promoter hypermethylation, predisposing carriers to breast and ovarian cancer." (PMID 40495194, 2025). "Notably, analogous interactions have been observed in other malignancies; for example, elevated Pb levels correlate with increased ovarian cancer risk in BRCA1 mutation carriers, implicating Pb in exacerbating genetic susceptibility." (PMID 40687430, 2025). "The prevalence of BRCA1/2 mutation in general Chinese women (p1), the prevalence of breast/ovary cancer family history in general Chinese women (p50), and the BRCA1/2 mutation prevalence in FH + population (p51) were interrelated and affected the ICER of the FH-based strategy." (PMID 40567951, 2025). "Its cost-effectiveness was influenced significantly by the proportion of BRCA1/2 mutation carriers, the risk of developing ovary cancer in BRCA1/2 carriers, and the proportion of FH-positive individuals, while factors such as the cost of BRCA1/2 testing had a lesser impact." (PMID 40567951, 2025). "Given that the prevalence of pathogenic BRCA1 mutations varies between 24% and 41%, this suggests that potentially up to 70% of ovarian cancer cases might be anticipated and avoided at an early stage." (PMID 38542081, 2024). "Similarly, risk reduction surgery for individuals with a BRCA1/2 pathogenic variant can reduce breast and/or ovarian cancer risk to below general population levels." (PMID 38637700, 2024). "The apparent smaller effect on mortality in carriers of BRCA2 PGVs compared to BRCA1 PGVs may be due to the lower risk of ovarian cancer in carriers of BRCA2 PGVs as well as the more aggressive biological characteristics of BRCA1-associated BC." (PMID 38672070, 2024). "Therefore, where evidence is available, a distinction is made in the chapters listed between BRCA1/2-pV carriers and carriers of pV in another breast and/or ovarian cancer risk gene and those with pV in the Lynch genes." (PMID 39259360, 2024). "While mitomycin C is not used routinely in the treatment of HGSOC, it reportedly may have clinical utility in BRCA1 mutated ovarian cancers, particularly in heavily pre-treated and recurrent cancers with poor prognosis." (PMID 38711848, 2024).
ovarian carcinoma (continued). "However, real-world evidence from over 2000 advanced ovarian cancer patients demonstrated that 36% had mutations in BRCA1/2 or HRD and would thus be amenable to PARPi therapy." (PMID 39135999, 2024). "Hopefully, to possibly add another tool in helping to reduce the diagnostic time for patients with breast and/or ovarian cancer, our study brings new information about the most frequent mutations of BRCA1 and BRCA2 genes associated with breast or ovarian cancer in the Romania population." (PMID 38785549, 2024). "Additionally, these mutations elevate the lifetime risk of developing ovarian cancer to 39−40% for BRCA1 mutations and 11−18% for BRCA2 mutations." (PMID 38966174, 2024). "Exposure to certain heavy metals, such as lead or molybdenum, has been identified as a potential environmental factor that could further exacerbate the risk of ovarian cancer, including individuals with BRCA1 mutations." (PMID 39300540, 2024). "In the ovarian cancer subgroup, BRCA1 variants, mainly c.5266dupC was found." (PMID 39148954, 2024). "Notably, pathogenic germline BRCA1 mutations and methylated BRCA1 promoter methylation have been shown to be mutually exclusive in breast and ovarian cancer." (PMID 38542081, 2024). "However, BRCA1/2 mutations are only detected in a small fraction of breast and ovarian cancer patients around 10%, limiting the effective use of PARPi and other DDR drugs in the clinic." (PMID 38383600, 2024). "Similarly to BRCA1-mutated ovarian cancer cells, HRDhigh sarcoma cells showed higher sensitivity than HRDlow sarcoma cells to PARPi but no major differential response to chemotherapy." (PMID 39535612, 2024). "Similarly, the lifetime risk of ovarian cancer is 39% for BRCA1 carriers and ranges from 11 to 17% for BRCA2 carriers." (PMID 39240499, 2024). "However, other large studies are pending to better refine the molecular characterization of BRCA1/2-mutated ovarian cancers and tailor therapeutic strategies." (PMID 38544832, 2024). "Furthermore, 10% to 21% of women with BRCA1 mutations will present with ovarian cancer by age 50 years compared with only 3% to 5% of women with BRCA2 mutations." (PMID 39028933, 2024). "Likewise, among ovarian cancer patients free from selection biases, the rate of detection of variants in BRCA1/BRCA2 was roughly 20%, whereas the rate for MGP analysis ranged from 26% to 31%, corresponding to a 1.5-fold elevation." (PMID 38397209, 2024). "BRCA1 mutations predispose women to breast and ovarian cancer." (PMID 38790714, 2024). "Indeed, approximately 20% of epithelial ovarian cancer (EOC) patients exhibit mutations in breast cancer susceptibility gene 1 (BRCA1) and gene 2 (BRCA2), contributing to homologous recombination deficiency (HRD)." (PMID 39457020, 2024). "A preliminary study has demonstrated that this may be an effective approach in BRCA1 mutated ovarian cancer." (PMID 38711848, 2024). "Furthermore, loss of BRCA1 in human ovarian cancer cells suppresses nuclear R-loop formation, resulting in accumulation of RNA-DNA hybrids in the cytoplasm which have the potential to activate RIGI." (PMID 39159817, 2024). "Somatic BRCA1/2 mutations are present in an additional 5–7% of ovarian cancer cases." (PMID 39767562, 2024). "Therefore, genetic counseling, proper surveillance and customized interventions for BRCA1/2 carriers are essential to maximizing the benefits of monitoring, chemoprevention and risk-reducing surgeries for breast and ovarian cancers." (PMID 39421188, 2024). "BRCA1/2 germline mutation also confers better outcomes, especially in ovarian cancer patients." (PMID 38544832, 2024). "In 2022, the Hereditary Ovarian Cancer Clinical Study Group also showed in a case–control study with 1,733 matched couples that the use of an oral contraceptive in BRCA1/2-pV carriers leads to a significantly reduced risk of ovarian cancer (OR 0.59; 95% CI 0.49–0.71)." (PMID 39259360, 2024).
ovarian carcinoma (continued). "Despite it being well established that heterozygous mutations in BRCA1 predispose women to develop breast and ovarian cancer at a very early age, only recently was it discovered that biallelic mutations in BRCA1 cause a FA-like neurodevelopmental disorder designated complementation group S (FANCS)." (PMID 38985307, 2024). "In addition, loss of RAD51C promoter methylation has also been reported to confer PARPi resistance, with loss of methylation in a single copy being sufficient to cause PARPi resistance, as was previously shown in BRCA1-hypermethylated ovarian cancers." (PMID 38544832, 2024). "Besides, 9 out of 16 ovarian cancer cases (56.3%) harboured genetic variants: six BRCA1 (37.5%), two RAD51C (12.5%) and in one case BRCA2 (6.25%)." (PMID 39148954, 2024). "Interestingly, this BRCA1 c.3232T > A variant found associated with endometriosis is located within an OCCR (c.1380–4062) of BRCA1 and mutations in this region of BRCA1 are known to be characterized as pathogenic in ovarian cancers." (PMID 39359934, 2024). "In contrast to breast and ovarian cancers, BRCA1/2 germ-line alterations, although being presumably a cause of LC disease in mutation carriers, are not always accompanied by the loss of the remaining BRCA1/2 allele, so they are not necessarily associated with tumor sensitivity to PARP inhibitors." (PMID 38966170, 2024). "Additionally, mutated BRCA1 increases ER-α expression levels in ovarian cancer cells, indicating tissue specificity." (PMID 38543119, 2024). "In 13–15% of ovarian cancer cases, germline BRCA1/2 mutations are found." (PMID 39767562, 2024). "Therefore, the identification of BRCA1/2 carriers in a presymptomatic stage is the ultimate goal to improve the prognosis for individuals at risk of hereditary breast and ovarian cancer." (PMID 39529133, 2024). "Additionally, oral contraceptives have been reported to reduce ovarian cancer risk by 50–55% in BRCA1 mutation carriers and by 40% in BRCA2 mutation carriers." (PMID 39590130, 2024). "Blood molybdenum level is a maker of ovarian cancer risk on BRCA1 mutation carriers." (PMID 39300540, 2024). "Ovarian cancer cells with mutations in BRCA1, BRCA2, or genes involved in the HR mechanism have an Homologous Recombination Deficiency (HRD) status, which renders them highly dependent on the DNA single-strand break (SSB) repair mechanism to maintain genomic stability." (PMID 39314634, 2024). "It is now clear that BRD4 could serve as a novel target in ovarian cancer like BRCA1/2 mutations and HR deficiency." (PMID 38893083, 2024). "Hence, there is ongoing research into constitutive BRCA1 promoter methylation as a potential diagnostic biomarker in relation to the risk of developing breast and ovarian cancer." (PMID 38542081, 2024). "CDCA and DCA could upregulate BRCA1 and downregulate ESR1 expression to inhibit BRCA1 mutated ovarian cancer progression." (PMID 38444942, 2024). "Poly (adenosine 5′-diphosphate-ribose) polymerase inhibitors (PARPi) have significantly improved maintenance therapy for recurrent ovarian cancer and are now approved as a first-line treatment for women with breast cancer susceptibility gene 1/2 (BRCA1/2) mutations." (PMID 38798714, 2024). "Through modified segregation analysis of 30 families, this variant was shown to have reduced penetrance, compared with the average penetrance truncating BRCA1 mutation (p = 0.0002), with estimated cumulative risks to age 70 of breast or ovarian cancer of 24%19." (PMID 39488595, 2024). "The high-grade diagnoses of BRCA-related ovarian cancer, exceeding 70%, and the lack of correlation between cancer grade and age at diagnosis highlight the urgency of understanding the impact of BRCA1-BRCT domain mutations in the context of ovarian cancer susceptibility." (PMID 38543119, 2024).
ovarian carcinoma (continued). "The female carrier of this pathogenic variant in Family 13 had gastric cancer and was assessed for pathogenic variants in other genes; after the variant in the BRCA1 gene was identified, the patient underwent surveillance, and breast and ovarian cancer were detected." (PMID 39438962, 2024). "Our study shows an uptake rate of 96.1% in BRCA1‐2 PV carriers referred for first counselling to a specialised centre that focuses on individuals with genetic susceptibility to ovarian cancer, which is higher than the rates previously reported in the literature." (PMID 39624976, 2024). "The loss of function in BRCA1 protein is a common mechanism for breast and ovarian cancer." (PMID 38785549, 2024). "The most important genes associated with hereditary breast and ovarian cancers are BRCA1 and BRCA2." (PMID 38928478, 2024). "Regarding ovarian cancer, this mechanism may also serve as an additional explanation for the positive selection of BRCA1/2 mutations." (PMID 38247798, 2024). "A review of published patient data from the United States, the United Kingdom, and Australia found that in ovarian cancer, the frequency of BRCA1 mutations in different countries ranged from 3.4% to 47%, and the frequency of BRCA2 mutations ranged from 1% to 12%." (PMID 38817903, 2024). "BRCA1 mutations substantially elevate the risks of breast and ovarian cancer." (PMID 38732616, 2024). "BRCA1, a gene linked to breast and ovarian cancers, also impacts melanoma." (PMID 39061157, 2024). "Key elements in the fight against ovarian cancer include access to molecular diagnostics, awareness of the presence of BRCA1 or BRCA2 gene mutations in the family, the use of effective treatment methods at an early stage of the disease, and improvement in the quality of comprehensive treatment." (PMID 38473394, 2024). "The prevalence of ovarian cancer is also higher in BRCA1 mutation carriers." (PMID 39028933, 2024). "Therefore, ovarian hyperstimulation for fertility treatment in BRCA1/2-pV carriers or pV-carriers in other risk genes for breast and ovarian cancer can be performed." (PMID 39259360, 2024). "However, this has to be seen in relation to the 20.5% of the ovarian cancer patients with germline BRCA1/2 mutations." (PMID 39003306, 2024). "BRCA1 is one of the most frequently mutated genes in human breast and ovarian cancers." (PMID 38734703, 2024). "Germline pathogenic variants in BRCA1 confer high risks of breast and ovarian cancers." (PMID 38063999, 2024). "BRCA1-related EOC represents an entity of ovarian cancers implicated in some EOC cases." (PMID 39502381, 2024). "We used a BRCA1-mutated ovarian cancer cell line as a positive control for PARPi response." (PMID 39535612, 2024). "It has been shown that changes in the balance between BRCA1 FL and the naturally occurring BRCA1 Δ11 isoforms may predispose to breast and ovarian cancer and promote resistance to PARPi." (PMID 39062754, 2024). "We observed an increased risk of ovarian cancer according to iodine levels in the BRCA1 carriers." (PMID 38892720, 2024). "In addition, breast and ovarian cancer survivors carrying a BRCA1/2 genetic mutation are also at a greater risk of having a local recurrence or a second cancer." (PMID 38192174, 2024). "The different associations between lead levels and the risks of breast and ovarian cancers may be associated with the mechanism of carcinogenesis in BRCA1 carriers." (PMID 38732616, 2024). "In October 2019, the Ministry of Food and Drug Safety of Korea approved olaparib as a first-line maintenance treatment for patients newly diagnosed with advanced, platinum-sensitive epithelial ovarian cancer with BRCA1 or BRCA2 pathogenic or likely pathogenic variants." (PMID 39590126, 2024). "Additionally, we reveal that the existing clinical data predict breast or ovarian cancers onset two years earlier for patients with BRCA1/2 mutations." (PMID 38279352, 2024).